HMMR (hyaluronan mediated motility receptor)
Diseases named in the same sentence as HMMR in open-access papers (continued):
Sharing a sentence is not in itself a finding about the gene and the disease.
lung carcinoma (continued). "Four genes (C1QTNF6, DLGAP5, HMMR, and PLEK2) were identified as key genes in LUAD progression, which were upregulated in the cancerous tissue compared with in the normal tissue (P < 0.001), and correlated with an unwanted prognosis in lung cancer (P < 0.05)." (PMID 37910672, 2023).
gastric cancer (27 papers, 2011 to 2025). A primary or metastatic malignant neoplasm involving the stomach. "As in gastric cancer, our previous research showed overexpression of HMMR caused chemotherapy resistance while silencing the expression of HMMR effectively increased the susceptibility to chemotherapeutic drugs." (PMID 36002694, 2022). "In gastric cancer patients, HMMR over-production was remarkably associated with tumor relapse and poor prognosis, and resulted in resistance to the chemotherapy via promoting epithelial-mesenchymal transition and modulating cancer stem cell properties." (PMID 35036134, 2021). "HMMR (RHAMM) is an oncogene that is overexpressed in several cancers, including gastric cancer, and has been implicated in many cellular processes, such as cell signaling, cell proliferation, and tumorigenesis." (PMID 22970268, 2012). "The HMMR signaling pathway endows gastric cancer cells with metastatic capacity by activating AKT signaling." (PMID 39086352, 2024). "An increased hyaluronan-mediated motility receptor (HMMR), a hyaluronan receptor, predicted poor survival, resistance to 5-FU, and increased stemness in gastric cancer." (PMID 38562556, 2024). "In summary, the results of the present study revealed through contacting with HA, HMMR exhibited as an oncogene to promote gastric cancer peritoneal metastasis by enhancing the cell–cell interactions and activation of AKT-FOXO1 signaling." (PMID 36002694, 2022). "In gastric cancer, it has been observed that the interaction occurring between hyaluronic acid and hyaluronan-mediated motility receptor (HMMR) is important in inducing 5-fluorouracil resistance." (PMID 36114508, 2022). "With the observation of tumor growth, Dox-induced silencing of HMMR potently reduced the ascites and peritoneal implantation of AGS-shHMMRDox, which suggested that the abrogate in HMMR potently reduced the peritoneal implantation of gastric cancer cells." (PMID 36002694, 2022). "Collectively, our findings highlighted the pro-metastatic role of HMMR, identifying HMMR as a novel prognostic biomarker and potential therapeutic target for gastric cancer." (PMID 36002694, 2022). "Silencing of HMMR expression markedly reduced the peritoneal metastasis of gastric cancer cells through reducing cell–cell interactions." (PMID 36002694, 2022). "The limitation of this study is detailed molecular mechanism by which HMMR activates AKT signaling in gastric cancer remains to be illuminated, which will be the main subject of our next research." (PMID 36002694, 2022). "Congruously, abdominal cavity injection of AGS cells with different HAS1 or HMMR expression also demonstrated HA was requisite for HMMR-mediated peritoneal implantation of gastric cancer." (PMID 36002694, 2022). "Consistently, either silencing HMMR or HAS1 significantly reduced the cell aggregation formation and increased the anoikis of gastric cancer cells, which suggested either HA or HMMR was necessary for cell–cell interaction of gastric cancer." (PMID 36002694, 2022). "For example, activation of the TGF-β/Smad2 signaling pathway mediated by HMMR contributes to the chemoresistance of gastric cancer." (PMID 34595101, 2021). "Many studies have found that HMMR is highly expressed in various malignant tumors, including bladder cancer, pancreatic cancer, glioma, gastric cancer, and colorectal cancer and so on." (PMID 33763352, 2021). "Extensive research had identified that the HMMR was overexpressed in non-small cell lung cancer, stomach cancer, bladder cancer, etc.." (PMID 34187556, 2021). "Expression of HMMR is upregulated in a variety of cancers, such as colorectal cancer 8, stomach cancer 9, endometrial cancer 10, prostate cancer 11, and multiple myeloma 12, and its high expression correlates with poor prognosis." (PMID 33061798, 2020). "Importantly, inducible depletion of HMMR significantly abrogates peritoneal implantation of gastric cancer in vitro and in vivo." (PMID 36002694, 2022).
gastric cancer (continued). "In this study, we demonstrated HMMR could increase the cluster formation through cell–cell contacts thus leading peritoneal metastasis of gastric cancer." (PMID 36002694, 2022). "We then asked whether depleting HMMR had an impact on peritoneal implantation of gastric cancer in vivo." (PMID 36002694, 2022). "Additionally, some patients with high HMMR expression may develop resistance to chemotherapy, leading to death, similar to what has been observed in prostate and gastric cancers." (PMID 39859458, 2025). "Finally, we assessed whether targeting HMMR might effectively abrogate peritoneal implantation of gastric cancer." (PMID 36002694, 2022). "The Hyaluronan Mediated Motility Receptor (HMMR) is responsible for the regulation of tumor cell motility, and its knockdown reduced peritoneal metastasis in gastric cancer." (PMID 38673800, 2024). "HMMR can induce epithelial-mesenchymal transition (EMT) and exert oncogenic effects through activating the TGF-β/Smad2 signaling pathway in gastric cancer." (PMID 33061798, 2020). "Compared with those without any metastasis, gastric cancer patients with peritoneal implantation exhibited higher expression level of HMMR and enhanced activity of AKT signaling." (PMID 36002694, 2022). "Furthermore, we assessed the clinical relevance of HMMR and AKT-FOXO1 signaling in gastric cancer specimens." (PMID 36002694, 2022).
multiple myeloma (23 papers, 2012 to 2025). "Targeting these elements by ASO demonstrated inhibition of HMMR-FL and splice variant V3 at mRNA and transcript levels and decreased micronuclei content, suggesting reduced genomic DNA damage in myeloma cells." (PMID 36737429, 2023). "Previous research has linked high HMMR expression to a bad prognosis in a variety of malignancies, such as breast, colorectal, gastric, endometrial, prostate, and multiple myeloma." (PMID 36750807, 2023). "Furthermore, HMMR expression has been observed in tumor stem cells, suggesting an important role in carcinogenesis; for example, in myeloma, elevated HMMR expression is associated with cytogenetic abnormalities." (PMID 39859458, 2025). "In multiple myeloma, several CTAs have been described by others and us, including MAGE-A3 (melanoma-associated antigen 3), NY-ESO-1 (New York esophageal-1), WT-1 (Wilms’ tumor gene 1), and RHAMM/HMMR (receptor of hyaluronic acid mediated motility)." (PMID 29156688, 2017).
prostate carcinoma (21 papers, 2012 to 2025). A carcinoma that arises from epithelial cells of the prostate gland. "Hyaluronan-mediated motility receptor (HMMR) is upregulated in prostate cancer and is associated with poor prognosis." (PMID 39196978, 2024). "HMMR is an oncogenic protein implicated in the progression of many human cancers, such as breast, gastric, and prostate cancers." (PMID 22666460, 2012). "Moreover, elevated HMMR expression is associated with poor prognosis in various cancers, including breast, colorectal, stomach, endometrial, and prostate cancers, as well as multiple myeloma." (PMID 38633247, 2024). "Although dysregulated HMMR is linked to prostate cancer (PCa) prognosis, the precise mechanisms remain unclear." (PMID 36750558, 2023). "The study found that the mutant T allele in HMMR-rs299295 and the G allele in STAB2-rs2271637 are associated with an increased risk of prostate neoplasm, including benign prostatic hyperplasia and prostate cancer (p < 0.001)." (PMID 40567905, 2025). "In prostate cancer, HMMR promotes proliferation and metastasis via the mTORC2/AKT pathway by inhibiting ubiquitination and increasing AURKA levels in vitro and in vivo." (PMID 39196978, 2024). "Genetic (siRNA) or pharmacological (4-MU) inhibition of HMMR significantly suppressed growth and induced apoptosis in hormone-sensitive and enzalutamide-resistant models of prostate cancer." (PMID 37673961, 2023). "HMMR inhibition was achieved via siRNA knockdown or pharmacological inhibition using 4-methylumbelliferone (4-MU) in prostate cancer cell lines, a mouse xenograft model and patient-derived explants (PDEs)." (PMID 37673961, 2023). "This study identified the hyaluronan-mediated motility receptor (HMMR) as a survival factor in prostate cancer and investigated its potential as a co-target for overcoming resistance to ARSIs." (PMID 37673961, 2023). "HMMR was originally identified as the receptor for hyaluronan (HA), a component of extracellular matrix, and it is frequently upregulated in various cancer types, including colon cancer, bladder cancer, prostate cancer, and liver cancer." (PMID 30867900, 2019). "Our study found a significant association between the mutant T allele in HMMR-rs299295 (A485V) and the mutant G allele in STAB2-rs2271637 (L2401V) variants and an increased risk of prostate neoplasm, including both groups (BPH, prostate cancer) compared to control men." (PMID 40567905, 2025). "In addition, HMMR promotes peritoneal implantation of gastric cancer by increasing cell-cell interactions and may promote prostate cancer proliferation and metastasis via the AURKA/mTORC2/E2F1 positive feedback loop." (PMID 38633247, 2024).
bladder cancer (20 papers, 2013 to 2025). "Among various tumors, in liver, stomach, lung, and bladder cancer, HMMR regulates proliferation and metastasis, preserves stemness, and confers resistance to treatment." (PMID 39911278, 2025). "Previous studies have emphasized that HMMR expression enhanced cell proliferation, the expression of mesenchymal markers and cell invasion in bladder cancer cells." (PMID 38429902, 2024). "Knockdown of HMMR significantly inhibited bladder cancer growth, invasion, epithelial-to-mesenchymal transition, and inactivation of the Wnt/β-catenin signaling pathway." (PMID 35311097, 2022). "The CD44 and Hyaluronan Mediated Motility Receptor (RHAMM) regulate the growth of bladder cancer cells." (PMID 29221154, 2017). "Moreover, in both endometrial tumors and non-small-cell lung cancer, high HMMR expression is correlated with a high tumor grade, and in bladder cancer, HMMR overexpression has been observed in areas of invasion, as well as in metastatic lung and colon tumors." (PMID 39859458, 2025). "The expression of HMMR may be an effective prognostic marker in progression-free survival of patients with the papillary subtype of bladder cancer." (PMID 33029143, 2020). "However the role of HA receptors CD44 and Hyaluronan Mediated Motility Receptor (RHAMM) in regulating the growth of bladder cancer cells driven by loss of AGL has not been studied." (PMID 27595989, 2016).
lung adenocarcinoma (20 papers, 2016 to 2026). A carcinoma that arises from the lung and is characterized by the presence of malignant glandular epithelial cells. "HMMR also associates with immune infiltration in lung adenocarcinoma, implying a role in CRC progression via immune microenvironment regulation." (PMID 41602397, 2026). "Our findings revealed that increased HMMR expression was linked to metastasis and poor prognosis in patients with lung adenocarcinoma (LUAD)." (PMID 39990663, 2025). "With the increasing risk score of patients with lymph node metastasis of lung adenocarcinoma, the expression of high-risk mRNAs (HMMR, B4GALT1, ANGPTL4, EXT1, GPC1, RBCK1, SOD1, AGRN) was obviously upregulated." (PMID 31847905, 2019). "Elevated HMMR levels were observed in both unpaired and paired lung adenocarcinoma tissues in comparison with normal ones." (PMID 39990663, 2025). "HMMR can also promote lung adenocarcinoma cell expansion in the metastatic niches of hyaluronan-rich microenvironments by enhancing extracellular matrix-mediated signaling." (PMID 39086352, 2024). "HMMR is overexpressed in lung adenocarcinoma tissues, and HMMR knockdown in lung adenocarcinoma inhibits cell proliferation, migration and invasion, while increasing apoptosis." (PMID 34925311, 2021). "As far as the regulation of HMMR is concerned, a HMMR antisense lncRNA, HMMR-AS1, can stabilize HMMR mRNA and promotes cancer progression in lung adenocarcinoma, glioblastoma, and epithelial ovarian cancer 57-59." (PMID 33061798, 2020). "Furthermore, research delving into the involvement of circRNAs and miRNAs in lung adenocarcinoma (LUAD) uncovered the high expression of hyaluronan-mediated motility receptor (HMMR) in LUAD, which correlates with clinical and pathological parameters." (PMID 38144204, 2023). "Moreover, HMMR has been extensively studied as a target for treating lung adenocarcinoma and glioma." (PMID 32241274, 2020). "Hyaluronan mediated motility receptor (HMMR) was overexpressed in a variety of tumors, and contributed to micro-metastasis of lung adenocarcinoma." (PMID 35954390, 2022). "MRNA expression levels of TIMP1, S100P, HMMR, F2RL1, KRT6A, and SLC2A1 were significantly increased in lung adenocarcinoma cell lines compared to16HBE, which were consistent with our bioinformatics analysis results." (PMID 35830566, 2022).
glioma (18 papers, 2015 to 2025). A benign or malignant brain and spinal cord tumor that arises from glial cells (astrocytes, oligodendrocytes, ependymal cells). "Firstly, We found that HMMR was highly expressed in gliomas by the analysis of the pan-cancer RNA-seq data from TCGA." (PMID 36750807, 2023). "This discovery stimulated preclinical immunogenic targeting of RHAMM in mouse glioma and melanoma models wherein mice received either dendritic cells pulsed with HMMR mRNA or a DNA-based xenopus RHAMM (xRHAMM), respectively." (PMID 36033439, 2022). "HMMR has recently been reported to express in the gliomas and to play a crucial role in self-renewal and tumorigenic potential of glioblastoma stem cells." (PMID 26466313, 2015). "Moreover, FOXM1 and HMMR genes, which promote stemness of glioma stem cells (GSC), resistant to apoptosis induced by oxidative stress and chemotherapy and regulation of tumor metastasis, are detected co-localized with TRIP13 gene." (PMID 34066132, 2021). "Although HMMR was shown to be overexpressed in GBM stem cells and might be used as a biomarker for gliomas, its predictive usefulness and putative function in gliomas were unknown and unproven." (PMID 36750807, 2023). "Finally, we need to further study the function and mechanism of HMMR and theHELLPAR/ RRM2 axis in gliomas by experiments." (PMID 36750807, 2023). "To further study the expression of HMMR, we compared the expression level of HHMR in glioma and normal tissues The expression level of HHMR in glioma was significantly higher than that in normal tissues (p < 0.01)." (PMID 36750807, 2023).
leukemia (18 papers, 2007 to 2025). A malignant (clonal) hematologic disorder, involving hematopoietic stem cells and characterized by the presence of primitive or atypical myeloid or lymphoid cells in the bone marrow and the blood. "Except for leukemia and some other cancers, HMMR expression in tumor tissues was significantly higher than in normal tissues." (PMID 36704516, 2022). "Hyaluronan-mediated motility receptor (HMMR) is an oncogene involved in neoplastic progression of human leukemias and solid tumors." (PMID 36250027, 2022).
liver cancer (15 papers, 2017 to 2025). An epithelial or non-epithelial malignant neoplasm that arises from the liver. "In different cancer types, HMMR is overexpressed, including acute myeloid leukemia and ovarian, pancreatic, kidney, and liver cancers." (PMID 39859458, 2025). "These genes, including RRM2, CCNB1, EZH2, and HMMR, are intricately involved in regulating essential cellular pathways and signaling cascades that are critical in the pathogenesis of liver cancer." (PMID 39118438, 2024). "HMMR is significantly overexpressed in patients with primary liver cancer and promotes the proliferation of liver cancer cells, which was reported in recent studies." (PMID 33540684, 2021). "The mRNA expression of 4 hub genes, includingCDK1, HMMR, PTTG1, and TTK, were significantly associated with the survival probability of liver cancer patients in TCGA." (PMID 34187556, 2021). "HMMR knockout inhibited liver cancer growth and induced phagocytosis." (PMID 38838151, 2024). "To investigate whether HMMR mediates the influence of FIGNL1 on ECM-receptor interaction pathway remodeling, we used HepG2 human liver cancer cell line to knock down HMMR on the basis of FIGNL1 overexpression." (PMID 37929733, 2024). "Single-cell sequencing and ligand-receptor relationship analysis in liver cancer have shown significant interactions between HA secreted by myCAFs and tumor receptors such as CD44 and HMMR." (PMID 40813707, 2025). "The mRNA levels and protein levels of CDK1, HMMR, PTTG1, and TTK were higher in liver cancer tissues compared to normal tissues, which showed excellent diagnostic and prognostic value." (PMID 34187556, 2021). "The correlation between the mRNA expression of CDK1, HMMR, PTTG1, TTK, and infiltrating immune cells in liver cancer was analyzed by using the TIMER database." (PMID 34187556, 2021). "Based on the protein expression data from the HPA, the protein expression levels of CDK1, HMMR, PTTG1, and TTK in liver cancer tissues and normal liver tissues were compared by utilizing the antibodiesCAB003799, CAB002433, HPA008890, and CAB013229." (PMID 34187556, 2021). "Notably, and in agreement with what was observed in the mouse models of liver cancer, ANLN, HMMR, TPX2, CCNB1, and CCNB2 expressions were found to be significantly upregulated in TCGA-LIHC." (PMID 37566034, 2023). "In addition to CCNB1, CDK1, CDC45, BUB1B, and CCNA2, we also identified five hub genes in Chinese liver cancer, namely AURKA, KIF11, TOP2A, TPX2, and HMMR, which play a crucial role in regulating the cell cycle." (PMID 34257537, 2021). "Furthermore, the relationship between SCNA of the CDK1, HMMR, PTTG1, and TTK and infiltrating immune cells in liver cancer was explored via using TIMER." (PMID 34187556, 2021). "Through the DGIdb, 69 drugs interacted with CDK1, HMMR, and TTK, which might help develop new treatment target for liver cancer therapy." (PMID 34187556, 2021). "Indeed, CEBPα overexpression increased HMMR mRNA and protein expression in HepG2 and MHCC-97H liver cancer cells, and OA further promoted CEBPα-stimulated HMMR expression." (PMID 33061798, 2020). "The immunohistochemistry results confirmed that the protein expression levels of CDK1, HMMR, PTTG1, and TTK were higher in liver cancer tissues than normal liver tissues." (PMID 34187556, 2021).
colorectal cancer (13 papers, 2008 to 2023). A primary or metastatic malignant neoplasm that affects the colon or rectum. "HMMR has been found markedly upregulated in colorectal cancer promoting growth, invasiveness, and dissemination of colorectal cancer." (PMID 36002694, 2022). "Among our 9 genes, HMMR has been found to be involved in many human solid carcinomas, including breast, non-small-cell lung, prostate, bladder, ovarian, and colorectal cancers, contributing to disease progression, aggressive phenotypes, and a poor prognosis in these patients." (PMID 31847905, 2019).
melanoma (13 papers, 2007 to 2025). A malignant, usually aggressive tumor composed of atypical, neoplastic melanocytes. "Among the genes predicting either melanoma metastasis or relapse were hyaluronan mediated motility receptor (HMMR), NIMA related kinase 2 (NEK2), and DNA-repair genes." (PMID 32878000, 2020).